GSDME (gasdermin E)
Diseases named in the same sentence as GSDME in open-access papers (continued):
Sharing a sentence is not in itself a finding about the gene and the disease.
gastric cancer (continued). "Epigenetic mechanisms result in inactivation of the GSDME gene in many types of cancer, including colorectal, breast, and gastric cancer." (PMID 31637008, 2019). "The epigenetic silencing of GSDME was first discovered in primary gastric cancer." (PMID 40756987, 2025). "In this study, we investigated the relationship between EBV infection, GSDME expression, and promoter methylation in gastric cancer using TCGA datasets and a panel of EBV-negative, artificially EBV-infected, and naturally EBV-infected gastric cancer cell lines." (PMID 41471908, 2025). "The results of quantitative analysis on GSDME expression in 97 cases of gastric cancer and 83 cases of normal gastric tissues indicated that GSDME exhibited high expression levels in gastric cancer tissues while being expressed at low levels in adjacent normal tissues." (PMID 38902235, 2024). "For instance, low expression of GSDME has been found in 52% of early-stage gastric cancer cases." (PMID 38902235, 2024). "Importantly, we demonstrate that ALKBH4 knockdown amplifies GSDME transcriptional activation, thereby facilitating chemotherapeutic drug-induced pyroptosis and ultimately enhancing the chemosensitivity of gastric cancer cells." (PMID 38902235, 2024). "Previous studies have demonstrated that treatment with 5-FU induces pyroptosis in gastric cancer cells, characterized by swelling and rupture of the cell membrane, and identified GSDME as a mediator of Caspase 3-dependent apoptosis to pyroptosis conversion in gastric cancer cells." (PMID 38902235, 2024). "Our findings indicate that the inhibition of ALKBH4 expression may enhance the sensitivity of gastric cancer cells to 5-FU by increasing the expression level of GSDME in gastric cancer." (PMID 38902235, 2024). "Although studies have confirmed that ALKBH4 is involved in the negative regulation of GSDME expression in gastric cancer cells, there are still many unknowns in other related pathways that ALKBH4 regulates pyroptosis." (PMID 38902235, 2024). "In gastric cancer, silencing GSDME can inhibit the development of cancer progression, indicating that GSDME-mediated cancer cell-specific pyroptosis may be a treatment target." (PMID 37500614, 2023). "Furthermore, GSDME knockout switched pyroptosis induced by 5-FU into apoptosis in gastric cancer cells." (PMID 38016064, 2023). "In 2007, epigenetic silencing of GSDME was initially discovered in primary gastric cancer." (PMID 38104141, 2023). "Therefore, GSDME’s capacity to suppress the proliferation of gastric cancer cells suggests that it can be utilized as a predictive biomarker." (PMID 38104141, 2023). "It’s worth noting that overexpression of GSDME in gastric cancer cells slowed down cell proliferation compared to that in control-group cells, suggesting that GSDME may play a role in tumor suppression." (PMID 38016064, 2023). "The analysis revealed that the high expression of GSDME in gastric cancer was found in ECM_RECEPTOR_INTERACTION, HYPERTROPHIC_CARDIOMYOPATHY_ HCM, DILATED_CARDIOMYOPATHY, GLYCOSAMINOGLYCAN_ BIOSYNTHESIS_CHONDROITIN_SULFATE, and FOCAL_ADHESION, which have important roles." (PMID 35419279, 2022). "The results showed that only GSDME had prognostic significance in gastric cancer." (PMID 35419279, 2022). "The knockdown of GSDME expression can inhibit the growth of gastric cancer cells." (PMID 35419279, 2022). "GSDME functions as a tumour suppressor gene in gastric cancer." (PMID 35896522, 2022). "The mutation of intron 7 in GSDME (DFNA5) is considered the cause of nonsyndromic hearing impairment 70, and recent cancer studies have indicated that its inactivation is to some extent related to gastric cancer." (PMID 34522213, 2021). "Moreover, our study also demonstrated that BIX combined Cis can induce GSDME‐mediated pyroptosis in gastric cancer cell lines." (PMID 32437063, 2020). "Reversed the lower expression of GSDME in gastric cancer by decitabine could improve the efficacy of chemotherapeutic drugs." (PMID 31616642, 2019).
gastric cancer (continued). "In gastric cancer (GC), the activation of pyroptosis-related genes (PRGs) such as GSDMD and GSDME is linked to favorable prognosis, while agents like famotidine, simvastatin, icariin, and diosbulbin-B trigger NLRP3 or caspase-3-mediated pyroptosis." (PMID 40806716, 2025). "Furthermore, evidence suggests that GSDME has prognostic significance in gastric cancer." (PMID 38104141, 2023). "Finally, the experimental analysis showed that knocking down the expression level of GSDME could affect the growth as well as apoptosis of gastric cancer cells." (PMID 35419279, 2022). "Therefore, the combination of BIX and Cis maybe a good treatment for the gastric cancer expressed very high level of GSDME or very low level of GSDME." (PMID 32437063, 2020). "Moreover, in 89 gastric cancer patient tissues, gasdermin E gene was hypermethylated in approximately 50% of the samples, and 5-aza-2′deoxycytidine, a methyltrasferase inhibitor, suppressed the growth of primary gastric cancer cells." (PMID 33348858, 2020). "However, the role of GSDME in chemotherapy for gastric cancers remains largely unclear." (PMID 32437063, 2020). "For example, quercetin induces pyroptosis in gastric cancer cells by increasing the expression of pyroptosis markers such as GSDMD, GSDME, and NLRP3 in a concentration-dependent manner." (PMID 39584140, 2024). "Famotidine, for instance, stimulated cell pyroptosis in gastric cancer cells by activating NLPR3 inflammasomes, which resulted in increased IL‐18 release and GSDME expression." (PMID 37752941, 2023). "Moreover, we administered dimethyl fumarate (DMF), a pyroptosis inhibitor for GSDME/GSDMD, to the cells and noted a reduction in cell mortality, indicating that ALKBH4 mediates the sensitivity of gastric cancer cells to 5-FU through GSDME." (PMID 38902235, 2024). "On the contrary, GSDME exhibits low expression levels in gastric cancer and demonstrates a negative correlation with poor prognosis among patients diagnosed with gastric cancer." (PMID 38902235, 2024). "However, GSDME expression is frequently silenced by promoter hypermethylation in multiple cancers, including gastric cancer, which prevents pyroptosis and favors non-inflammatory apoptosis." (PMID 41471908, 2025). "However, in the absence of GSDME, 5-FU-induced apoptosis was converted to apoptosis, suggesting that GSDME converts chemotherapeutic agent-induced apoptosis into gastric cancer cell death." (PMID 40756987, 2025). "However, GSDME deletion by CRISPR-Cas9 converted 5-FU-induced pyroptosis to apoptosis in SGC-7901 cells, indicating that GSDME converts chemotherapy drug-induced apoptosis to pyroptosis in gastric cancer cells." (PMID 38104141, 2023). "GSDME was present in all 10 lung and liver cancer cell lines, but absent in two (HGC27 and MKN28) of five gastric cancer cell lines." (PMID 32341339, 2020). "Additionally, recent studies have indicated that GSDME, rather than GSDMD, can switch chemotherapy-induced caspase-3-dependent cell apoptosis to pyroptotic cell death in gastric cancer cells." (PMID 38016064, 2023). "Furthermore, the cleavage of GSDME but not GSDMD was observed in the BIX + Cis combined treated group and the KO of GSDME significantly switched pyroptosis to apoptosis, which confirmed that BIX combined Cis induced pyroptosis in gastric cancer dependent on the cleavage of GSDME and caspase‐3." (PMID 32437063, 2020).
hearing loss (41 papers, 2012 to 2025). "This expands the mutational spectrum of GSDME-related hearing loss and reinforces the role of exon 8 as a hotspot for pathogenic variants." (PMID 41007806, 2025). "In line with this, familial DFNA5 hearing loss mutations that remove the C-terminal portion of GSDME lead to a constitutively active N-terminal fragment, resulting in spontaneous cochlear cell death." (PMID 41550939, 2025). "The results revealed that all of the affected individuals with hearing loss presented a 25‐bp heterozygous insertion (GGGGTGCAGCTTACAGGGTGGGTGT) in exon 8 of the GSDME gene (NM_004403.3: c.1113_1114)." (PMID 37864300, 2024). "In our study, we successfully identified a novel insertion variant of GSDME in exon 8 (GSDME: NM_004403.3: c.1113_1114insGGGGTGCAGCTTACAGGGTGGGTGT: p.P372fs*36) that segregated with the occurrence of hearing loss of the affected family." (PMID 37864300, 2024). "In conclusion, this study elucidated the molecular mechanism associated with hearing loss caused by GSDME gene mutations, offering novel insights for potential treatment strategies." (PMID 39066985, 2024). "GSDME (also known as ICERE-1 or DFNA5) was initially identified as a gene responsible for autosomal dominant non-syndromic hearing loss and was later found to possess sequence and structural similarities to the gasdermins." (PMID 37664463, 2023). "Hearing loss (HL), a sensory impairment, is caused by mutations in different genes, including GSDME." (PMID 35462927, 2022). "When GSDME was discovered as a gene associated with hearing loss, little was known about its physiological functions." (PMID 35462927, 2022). "Gain-of-function GSDME variants are also related to hearing impairment by enhancing a detrimental cytotoxic activity of GSDME." (PMID 35844522, 2022). "The gasdermin E gene (GSDME, also known as DFNA5) is mutated in familial aging-related hearing loss." (PMID 34433433, 2021). "Later, many other families suffering from hearing loss were also found to have GSDME (DFNA5) mutations." (PMID 34858408, 2021). "In this study, we have successfully identified a novel insertion variant in exon 8 of the GSDME gene (GSDME: NM_004403.3: c.1113_1114insGGGGTGCAGCTTACAGGGTGGGTGT: p.P372fs*36) associated with hearing loss in a large Chinese pedigree family, thereby expanding the variant spectrum." (PMID 37864300, 2024). "GSDME is a member of the gasdermin family, a gene originally implicated in hereditary hearing loss." (PMID 39157415, 2024). "The specific causative link between GSDME mutations and hearing impairment, while avoiding pathological damage to other organs where GSDME is highly expressed, remains unclear." (PMID 39066985, 2024). "We searched PubMed for all reported GSDME mutations that can lead to non-syndromic hearing loss." (PMID 36350814, 2022). "GSDME is variably expressed in a range of human cells and tissues, including the brain, endometrium, placenta and intestine and was characterized as the causative gene for nonsyndromic hearing loss and as a tumor suppressor." (PMID 35795683, 2022). "While these caspases can dismantle the cell to limit its immunogenic potential, caspase-3 has recently been documented to cleave (at 267 DMPD 270) and activate GSDME (or DFNA5, deafness autosomal dominant 5), a gene implicated in hearing loss and often silenced in cancer." (PMID 35608339, 2022). "In addition to its implication in hereditary hearing loss, the Gasdermin E (GSDME) gene is also a tumor suppressor involved in cancer progression through programmed cell death." (PMID 30993897, 2019). "Therefore, the aim of this study was to elucidate the mechanisms of HL caused by GSDME mutations at the organism and cellular levels and provide insight into new therapeutic strategies to mitigate the cytotoxicity of GSDME mutation-driven hearing impairment." (PMID 39066985, 2024).
hearing loss (continued). "Distinct roles for Gasdermin family proteins in neutrophils versus macrophages also applies to GSDME, which was first reported as a mutated gene (DFNA5) associated with hearing loss, but also forms plasma membrane pores following cleavage by caspase-31." (PMID 37730693, 2023). "GSDME, formerly called DFNA5, was first confirmed in an extended Dutch family with autosomal dominant nonsyndromic hereditary hearing loss." (PMID 34820376, 2021). "The mutation in exon 6 of GSDME (DFNA5) is not specific for hearing loss (HL)." (PMID 34858408, 2021). "Gasdermin E (GSDME), also known as DFNA5, belongs to the same superfamily as GSDMD, and was originally identified as a gene related to hearing impairment." (PMID 35972780, 2022).
deafness autosomal dominant 5 (28 papers, 2012 to 2025). "GSDME, also known as DFNA5 (associated with autosomal dominant non-syndromic deafness), has recently been identified as a critical factor in caspase-3-mediated pyroptosis, particularly in chemotherapy-induced scenarios." (PMID 41413917, 2025). "Variants in the gene GSDME (also known as DFNA5) are associated with autosomal dominant nonsyndromic hearing loss." (PMID 41020988, 2025). "Gasdermin E (GSDME) is a gene associated with autosomal dominant nonsyndromic hearing impairment and belongs to the gasdermin superfamily." (PMID 40256765, 2025). "Mutations in GSDME (also referred to as DFNA5) have been found to cause autosomal-dominant non-syndrome deafness; the mutations result in the skipping of exon 8 and have a gain-of-function effect." (PMID 40261527, 2025).
colon cancer (27 papers, 2019 to 2026). "Coxsackie virus group B3 exerts oncolytic activity in colon cancer cell lines via GSDME-mediated pyroptosis." (PMID 40721578, 2025). "Coxsackievirus B3 (CVB3) causes GSDME cleavage by activating caspase-3, ROS can also promote CVB3-induced pyroptosis, and CVB3 exhibits oncolytic activity in colon cancer cell lines through GSDME-mediated pyroptosis." (PMID 39011036, 2024). "One of these is pyroptosis, which occurs through the activation of caspase 3 via the cleavage of gasdermin E. This type of cell death was detected in colon cancer cell lines." (PMID 39457005, 2024). "The signal transduction pathway involving reactive oxygen species (ROS) and c-Jun N-terminal kinase (JNK) was activated by lobaplatin treatment, leading to the initiation of gasdermin E (GSDME)-mediated pyroptosis in cells of colon cancer origin." (PMID 37998025, 2023). "For example, lobaplatin induces caspase-3/GSDME-mediated pyroptosis by increasing ROS levels in colon cancer cells." (PMID 37679782, 2023). "Similar to CVB3, lopressor can promote ROS phosphorylation and activate the caspase-3/GSDME axis to induce colon cancer cell pyroptosis." (PMID 38104141, 2023). "Recent studies have shown that the BAK/BAX and caspase-3/GSDME axis mediates chemotherapy-induced pyroptosis in colon cancer cells." (PMID 38104141, 2023). "This was consistent with a previous study showing that some chemotherapy drugs can induce pyroptosis in colon cancer cells by CASP3 cleavage of GSDME." (PMID 36127676, 2022). "It was reported that apoptin triggered caspase-9/caspase-3/GSDME-dependent pyroptosis of colon cancer cells through mitochondrial related ROS pathway and significantly inhibited tumor growth in vivo." (PMID 36505474, 2022). "In colon cancer cells, the cleavage of GSDME by caspase-3 was crucial for the lobaplatin-induced pyroptosis." (PMID 36127654, 2022). "Based on the results with these two cell lines, we established that CVB3 infection is mainly mediated via the casp-3/GSDME pathway, leading to pyroptosis of colon tumor cells." (PMID 36551691, 2022). "Our findings indicate that CVB3 has oncolytic activity in colon cancer cell lines via GSDME-mediated pyroptosis." (PMID 36551691, 2022). "In summary, we demonstrate that CVB3 induced pyroptosis in colon cancer cell lines, that this was dependent on GSDME degradation downstream of casp-3, and that elevated ROS were required for casp-3/GSDME activation." (PMID 36551691, 2022). "Kim used 5-Aza-DC to activate silenced genes in colon cancer and found that GSDME was activated the most frequently, in up to 40% of cases." (PMID 35351070, 2022). "In AOM/DSS mice, QCWZD reduced the occurrence of colonic tumors by improving the function of the intestinal barrier and inhibiting GSDME-mediated pyroptosis." (PMID 35910578, 2022). "This leads to production of GSDME N-termini and the development of pores in the plasma membrane, inducing pyroptosis of colon cancer cell lines." (PMID 36551691, 2022). "Our findings indicate that WT-CVB3 has a therapeutic effect against colon cancer via GSDME-mediated pyroptosis." (PMID 36551691, 2022). "For example, lobaplatin induced caspase-3/GSDME-mediated pyroptosis by increasing cellular ROS levels in colon cancer cells." (PMID 33558527, 2021). "DAC is performed in advance using specific tumor-bearing mice to demethylate the GSDME gene in mouse colon cancer cells and breast carcinoma cells." (PMID 32093389, 2020). "Activated JNK further enhanced Bax translocation to the mitochondria, consequently activating caspase-3, and ultimately inducing the cleavage of GSDME and pyroptosis of colon cancer cells." (PMID 30804337, 2019). "In the present study, we demonstrated that lobaplatin induces ROS/JNK signalling to induce the pyroptosis of colon cancer cells via a novel Bax-caspase-GSDME pathway." (PMID 30804337, 2019).